NLRP3 (NLR family pyrin domain containing 3)
Diseases named in the same sentence as NLRP3 in open-access papers (continued):
Sharing a sentence is not in itself a finding about the gene and the disease.
tumor (continued). "Dysregulation of NLRP3 inflammasome is involved in tumor pathogenesis." (PMID 34393801, 2021). "Studies to date suggest that the tumor-intrinsic NLRP3 inflammasome plays an important role in recruiting the highly immunosuppressive PMN-MDSCs into the tumor microenvironment and facilitating tumor immune evasion as well as resistance to checkpoint inhibitor immunotherapy." (PMID 34638239, 2021). "Next, we analyzed whether the additive effect seen with NLRP3 inhibition on tumor growth was T cell-mediated or a direct effect on tumor cell proliferation." (PMID 33649199, 2021). "In line with this, the NLRP3 inflammasome pathway has been described to have a procarcinogenic effect in hep3B cells, in which tumor-suppressive miR-223 promotes apoptosis and inhibits the proliferation of HCC cells by negatively regulating NLRP3 and downstream cytokines." (PMID 34064909, 2021). "Moreover, studies have shown that among tumor-infiltrating immune cells, macrophages promote lymphangiogenesis via NLRP3-dependent IL-1β secretion." (PMID 34737710, 2021). "There was a significant difference in tumor development and metastasis in mice injected with NLRP3 WT(+/+) SK-Hep1 Luc cells as compared with mice injected with NLRP3 KO(−/−) HCC cells beginning in the fifth week, and this difference increased when the mice were treated with NK-92 cells." (PMID 34502191, 2021). "Future studies to uncover tumor-selective regulators of the NLRP3 inflammasome may allow for the development of pharmacologic agents that avoid impacting myeloid cell inflammasome activity and thus circumvent the development of potential off-target toxicities." (PMID 34638239, 2021). "The involvement of NLRP3-driven inflammation adds extra impetus to such treatment as it has been shown that NLRP3 activation in various tissues can activate NK cell responses, which could contribute to the clearance of tumor." (PMID 33840390, 2021). "Indeed, additional experiments both in vitro and in vivo using both genetic silencing and pharmacologic inhibition demonstrated the release of tumor HSP70 to be dependent on activation of the tumor-intrinsic NLRP3 inflammasome." (PMID 34638239, 2021). "It appears that the effect of NLRP3 activation on tumor growth depends on the stimulus." (PMID 33613529, 2020). "Interestingly, after combined LPS/Nigericin treatment, tumor cells demonstrated two distinct patterns of NLRP3 inflammasome activation." (PMID 33613529, 2020). "RACK1 may act via a variety of processes in tumours, including upregulating the assembly and activity of the NLRP3 inflammasome, miRNAs patterning, and AhR regulation." (PMID 33375613, 2020). "However, earlier studies have also implicated, for example, ASC, NAIPs, NLRP3 and NLRP6 as tumour suppressors." (PMID 32068945, 2020). "HUVECs were maintained in a culture medium from each tumor cell line after NLRP3 modulation." (PMID 33613529, 2020). "Our data demonstrate that MIF production could be involved in NLRP3 activation in tumor cells treated with Nigericin." (PMID 33613529, 2020). "Additionally, for the first time, we have demonstrated that cell death caused by LPS/Nigericin treatment, produced variable effects on tumor cells, depending upon their NLRP3 activation level and cytokines released." (PMID 33613529, 2020). "Elevations in O-GlcNAcylation are associated with increased NLRP3 inflammasome and NF-κB signalling activity, with the NLRP3 inflammasome important to cancer progression and tumour microenvironment regulation, with effects at least partly regulated by the O-GlcNAcylation of RACK1." (PMID 33375613, 2020). "In addition, the study revealed that IOP promotes NLRP3 inflammasome activation, thereby exerting anti-tumor effects." (PMID 33603669, 2020). "Notably, ATP released from dying tumor cells mediates immunogenic cell death via the activation of the NLRP3 inflammasome." (PMID 33304353, 2020).
tumor (continued). "We found that, when the NLRP3 inflammasome is activated, two groups of tumor cells could be identified based on LDH release and IL1β secretion." (PMID 33613529, 2020). "Additionally, ergosterol peroxide treatment inhibited tumor cell proliferation and migration by attenuating NLRP3 inflammasome activity." (PMID 32703253, 2020). "The NLRP3 inflammasome and its down-stream pathways could be considered novel potential tumor biomarkers and could open new frontiers in BC treatment." (PMID 33014808, 2020). "Despite accumulating evidence supporting NLRP3-mediated immune evasion, the inflammasome has also been reported to activate pro-surveillance pathways that heightened anti-tumor control and prevented tumor metastasis." (PMID 33613533, 2020). "Genetic or pharmacological inhibition of the NLRP3 complex resulted in the restoration of innate and adaptive anti-tumor immune response, suggesting that NLRP3 may represent a suitable target to sensitize PDAC to immunotherapy." (PMID 32509781, 2020). "Arsenic accumulation in tumor tissues was observed to cause down-regulation of ROS levels and a significant reduction in hypoxia-inducible factors-1α (HIF-1α) expression, leading to the inhibition of NLRP3 expression." (PMID 33014808, 2020). "However, contradicting studies regarding the role of NLRP3 inflammasome activation in CRC development have been published ranging from tumor promoting to tumor-preventing modes of action." (PMID 33102234, 2020). "Collectively, these results revealed that BRD4 inhibition-elicited repression of EMT progression and proliferation and inducement of pyroptosis in RCC cells were mediated by NLRP3, and that NLRP3 might function as a tumor suppressor." (PMID 32303673, 2020). "NLRP3 triggers innate immunity by activating caspase-1 and then cleaves immune and metabolic substrates, especially the pro-inflammatory cytokine interleukin-1β (IL-1β), which induces inflammation and promotes tumor growth." (PMID 32435622, 2020). "Therefore, we first analyzed mRNA expression of Caspase-1, PYCARD, and NLRP3 in paired normal and tumor tissues collected from CRC patients by qPCR experiments." (PMID 33102234, 2020). "Moreover, the NLRP3 inflammasome was shown to promote tumor growth in models of carcinogen-induced sarcoma and skin papilloma through the release of IL-1β." (PMID 33042810, 2020). "This signal facilitated tumor progression, which was attenuated when NLRP3 or IL‐1β was inhibited." (PMID 32508035, 2020). "However, CAPE did not affect NLRP3 or IL-1β transcription, but instead enhanced NLRP3 binding to ubiquitin molecules, promoting NLRP3 ubiquitination, and contributing to the anti-tumor effect in the AOM/DSS mouse model." (PMID 32435622, 2020). "Besides NLRP3, other types of inflammasomes have been identified in playing specific roles in tumor progression and metastasis." (PMID 33015196, 2020). "Another link for NLRP3 to the adaptive immune system is related to tumor responses." (PMID 33036374, 2020). "In summary, these data supported our in vivo findings and verified our assumption that IOP might play an anti-tumor effect by promoting the activation of NLRP3 inflammasome." (PMID 33603669, 2020). "However, antitumor immunity of T cells was inhibited by NLRP3 inflammasome in the tumor microenvironment." (PMID 32974137, 2020). "However, the present study is the first study to examine the expression of the NLRP3 inflammasome in LSCC tumor tissues and investigate the correlation between its expression and the prognosis of LSCC without distant metastasis in a Chinese population." (PMID 31312615, 2019). "Thus, expression of NLRP3 in CAFs is important for tumour growth, and mediates the recruitment of CD11b+Gr1+ myeloid cells into the tumour microenvironment." (PMID 31558756, 2019).
tumor (continued). "Strikingly, while control mammary fibroblasts augmented tumour growth, genetic depletion of Nlrp3 or Il1b in injected fibroblasts significantly attenuated tumour growth and weight, suggesting that CAF-derived inflammasome is functionally important for tumour growth in vivo." (PMID 31558756, 2019). "The reason for these different results may be related to the type of tumor and the role of the NLRP3 inflammasome in different tumor microenvironments." (PMID 31312615, 2019). "MDSC-derived TAM release cathepsin B to activate the Nlrp3 inflammasome to promote tumor growth." (PMID 31629410, 2019). "These suggest that the activation of NLRP3 inflammasome in macrophages by ATP of which level is high in tumor microenvironment, results in the increased production of IL-1β and the promotion of tumor cell metastasis." (PMID 31439870, 2019). "Thus, tumour-related DAMPs can activate fibroblasts to functionally express the NLRP3 inflammasome and pro-inflammatory signalling." (PMID 31558756, 2019). "Histopathological examination found LPS-induced pulmonary inflammatory changes enhanced lung tumorigenesis induced by B(a)p in WT mice, deletion of NLRP3 improved the inflammatory changes induced by LPS and the number and size of pathological tumor nests induced by B(a)p or B(a)p plus LPS." (PMID 30696442, 2019). "The NLRP3 inflammasome has been identified as a putative oncogene in non-small cell lung cancer genomic analyses, however, recent evidence suggests that it also has tumor suppressor function." (PMID 31510091, 2019). "Analysis of tumour growth revealed that tumours co-injected with Nlrp3−/− NMFs were significantly smaller than tumours injected with WT fibroblasts, suggesting that expression of NLRP3 in CAFs supports tumour growth." (PMID 31558756, 2019). "Therefore, the results further provide a beneficial strategy for preventing tumor metastasis by regulating NLRP3 inflammasome in immune cells and thereby reducing IL-1β levels in tumor sites." (PMID 31439870, 2019). "Moreover, CAF-derived inflammasome signalling facilitated tumour growth and metastasis, which was attenuated when NLRP3 or IL-1β were specifically ablated." (PMID 31558756, 2019). "With the knowledge that IL-1β, NLRP3-inflammasome and EVs have a pivotal role in the establishment of tumour microenvironment, the contribution of EVs released from advanced-stage PCa cells on the behaviour of microenvironment-residing or infiltrating non-cancerous cells has never been investigated." (PMID 31480312, 2019). "Depending on the tumor types and tissues, NLRP3 inflammasome could have either protective or aggravating effects on tumor growth or metastasis." (PMID 31156650, 2019). "We next investigated whether the activation of NLRP3 inflammasome in immune cells in tumor microenvironment contributed to promoting metastatic potential of cancer cells." (PMID 31439870, 2019). "Univariate and multivariate Cox regression analyses (including age, smoking, alcohol consumption, stage of LSCC, histological grade, and tumor diameter) were also used to determine the relationship between NLRP3 inflammasome expression and the survival of LSCC patients." (PMID 31312615, 2019). "It has been shown that the NLRP3 inflammasome inhibits tumor growth in colorectal cancer." (PMID 31510091, 2019). "Furthermore, our results indicate the essential role of S100A9 in tumor-environment interactions in bone marrow and greatly improve our understanding of the role of the NLRP3 inflammasome in cellular senescence." (PMID 31727865, 2019). "Furthermore, it was well documented that NLRP3 inflammasome plays a vital role in tumor development." (PMID 30696442, 2019). "Our results confirmed that BBR can effectively affect both tumor outgrowth and spontaneous metastasis in TNBC, and that we identified a new mechanism associated with inhibition the NLRP3 inflammasome pathway, suggesting its potential therapeutic relevance in clinical use." (PMID 31412862, 2019).
tumor (continued). "However, the use of synthetic compounds or small molecule inhibitors for in vivo targeting of NLRP3 and examining the infiltrating lymphocytes in the tumor bed are just at the initial stage." (PMID 30631327, 2018). "Additionally, overexpression of XLOC_000647 resulted in a decreased expression of NLRP3 in PC cell lines and tumor tissues from nude mice." (PMID 29386037, 2018). "Further investigation has demonstrated that this cascade of events is initiated by CD8+ T cell-dependent stimulation of the NLRP3 inflammasome in tumor cells which drives the release of HSP70 and serves to dampen the efficacy of anti- PD-1 antibody immunotherapy." (PMID 30400822, 2018). "However, the activation and function of NLRP3 inflammasome in other cells of the OSCC tumor microenvironment needs more exploration." (PMID 29716544, 2018). "Downregulating NLRP3 expression in OSCC cells significantly reduced the tumor growth in vivo." (PMID 29716544, 2018). "However, studies are emerging that aim to determine the role of NLRP3 in the regulation of immune cells in a tumor setting." (PMID 30631327, 2018). "By contrast, in the lung microenviroment the decreased TLR4/NLRP3 axis could represent a tumor mediated immunosuppression." (PMID 30365491, 2018). "Furthermore, western blot and IHC results indicated that overexpression of XLOC_000647 resulted in a decreased expression of NLRP3 in PC cell lines and tumor tissues from nude mice compared with their corresponding control groups." (PMID 29386037, 2018). "Data demonstrated that the silencing of NLRP3 distinctly reduced the tumor sizes and weights." (PMID 29716544, 2018). "In this regard, NLRP3 can decrease NK cell activation and lead to tumor invasion." (PMID 30447690, 2018). "Thus, NLRP3 inflammasome and its products can directly promote the growth of tumor cells and drug resistance." (PMID 29312552, 2017). "Researches have confirmed that chemotherapy drugs could induce the production of NLRP3 inflammasome, activate the caspase-1 molecules and induce secretion of IL-1β, which can inhibit the anti-tumor effect of chemotherapy." (PMID 29312552, 2017). "Moreover, activated NLRP3 inflammasome restrained the antitumor efficacy and promoted tumor growth when gemcitabine and 5-fluorouracil were used for cancer cell treatment." (PMID 28865486, 2017). "In addition, blockade of NLRP3 inflammasome can also delayed the tumor-burdened speed in SCCHN mice." (PMID 28865486, 2017). "Results from hierarchy clustering and linear regression analyses showed that the expression of tumor-associated ASC and IL-18 are closer to ALDH1 expression, NLRP3 and Caspase-1 are close to ALDH1 expression, and NLRP3, Caspase-1, ASC, and IL-18 are close to CD44 and BMI1 expression." (PMID 28865486, 2017). "IL-18, another effector molecule of NLRP3 inflammasome, could inhibit the growth of NK cells to promote tumor growth and metastasis by inducing the expression of PD-1." (PMID 29312552, 2017). "Because when the tumor occurs, the NLRP3 inflammasome was activated and produced IL-1β to form an inflammatory microenvironment and promoted tumor progression, and the progressive tumors would further stimulate NLRP3 inflammasome to produce more IL-1β." (PMID 28865486, 2017). "Moreover, it is well known that DAMPs, such as ATP, are responsible of NLRP3 activation as well as it is highly produced in the tumor lesion." (PMID 27528423, 2016). "Increasing evidence validates that dying tumor cells following chemotherapy might activate the NLRP3 inflammasome of dendritic cells via P2×7 purinergic receptors, thus priming tumor-specific interferon-γ-producing T lymphocytes to limit cancer growth." (PMID 27206676, 2016). "It has been suggested that NLRP3 activation could suppress NK and T cell-mediated anti-tumor actions in a sarcoma mouse model and metastatic melanoma, whereas the population of myeloid-derived suppressor cells and Tregs were increased." (PMID 27206676, 2016).
tumor (continued). "In addition, MM tumor tissue arrays stained for NLRP3 protein confirmed the results of MM tumors of low NLRP3 protein levels (red-NLRP3 protein, green-nucleus)." (PMID 26689911, 2015). "Seven different MM tumor cell lines were assessed for NLRP3 mRNA levels relative to LP9." (PMID 26689911, 2015). "Besides interfering with natural tumor control, NLRP3 inflammasome-mediated IL-1β has been described to attenuate anti-tumor effects of chemotherapeutic agents, gemcitabine (Gem), and 5-fluorouracil (5FU)." (PMID 25071785, 2014). "This study suggests that the immunosuppressive role of the NLRP3 inflammasome may reduce the effectiveness of DC derived anti-tumor vaccines." (PMID 24474192, 2014). "Tumor-associated MDSC may suppress natural killer (NK) cells, which would explain why loss of NLRP3 increases the anti-metastatic function of NK cells in a B16-F10 lung metastasis model." (PMID 24474192, 2014). "Furthermore, they reported that NLRP3-inflammasome activation in hematopoietic cells is critical for the tumor suppressive function, which has been attributed to IL-18 production." (PMID 24474192, 2014). "Moreover, NLRP3 expression in myeloid cells was shown to interfere with the suppression of cancer metastasis by inhibiting recruitment of anti-tumor NK cells to the site of carcinogenesis." (PMID 25071785, 2014). "Importantly, it was shown that the presence of NLRP3 in hematopoietic cells was necessary for this the tumor-suppressing effect in response to AOM-DSS challenge." (PMID 24273542, 2013). "Thus, overexpression of AIM2, RIG-I and NLRP3 inflammasomes and IL-1β in tumour cells likely contributes to local tumour control." (PMID 23065753, 2012). "Extracellular ATP can also function through P2RX7 purinergic receptors to initiate NLRP3 inflammasome activation and subsequent IL-1β production that were all shown to be required for the induction of tumor antigen-specific CD8+ T cells following challenge with dying tumor cells." (PMID 23087904, 2012). "Furthermore, P. gingivalis could promote colorectal tumorigenesis by fostering a proinflammatory tumor microenvironment via the activation of the NLRP3 inflammasome." (PMID 41181349, 2025). "Additionally, STING activation can trigger the NLRP3 pathway, leading to direct tumor cell death." (PMID 40520004, 2025). "Similarly, FL118 exerts its tumor-suppressive effects by activating the NLRP3 inflammasome, which promotes caspase-1 activation and upregulates GSDMD expression, thereby inhibiting the proliferation, migration, and metastasis of CRC and pancreatic cancer cells." (PMID 41267084, 2025). "The dynamic interactions with the TME could be assessed using advanced imaging techniques such as multiplex immunohistochemistry to visualize NLRP3 localization and tRNA alterations in situ, providing a better understanding of how these interactions contribute to tumor progression." (PMID 40718836, 2025). "A study found inhibiting the activity of NLRP3 inflammasome may have anti-tumor effects." (PMID 40535567, 2025). "Moreover, elevated levels of NLRP3 may correlate with the proliferation of tumor cells and their ability to withstand therapeutic interventions." (PMID 40008397, 2025). "Additionally, lower NLRP3 levels were observed in RCC tumor samples, suggesting that NLRP3 may act as a tumor suppressor in RCC." (PMID 40718836, 2025). "In parallel, clinical trials could assess the combination of PARP inhibitors with NLRP3-targeted therapies in patients with high NLRP3 expression, evaluating treatment efficacy by monitoring tumor progression, DNA repair markers (e.g., γ-H2AX), and patient response rates." (PMID 40718836, 2025). "In addition, OSCC is characterized by hypoxia and ROS accumulation, or other common metabolic abnormalities that may further exacerbate inflammation and tumor invasion by the activation of NLRP3." (PMID 41560727, 2025).